FOXP3 (forkhead box P3)
Diseases named in the same sentence as FOXP3 in open-access papers (continued):
Sharing a sentence is not in itself a finding about the gene and the disease.
glioma (continued). "Our data suggest that CD4+ and perivascular Foxp3+ TILs impact angiogenesis and tumor recurrence in patients with gliomas." (PMID 29163521, 2017). "Instability of FOXP3 induced by U87 supernatants would seem at odds with the demonstrated increased intratumoural Treg fractions found in glioma patients." (PMID 28239749, 2017). "On the other hand, a flow cytometric analysis of glioma tissues from 31 patients showed the presence of immune-suppressive IL-17+FoxP3+ T cells (8% in gliomas versus 0.5–1% in control tissues)." (PMID 26755664, 2016). "Second, since it has been recently reported that glioma cells also expressed Foxp3, our data based on immunohistochemistry were prone to interpreting the biologic behavior of Foxp3 expression more than exact TILs." (PMID 24276989, 2014). "CD4+FoxP3+ Tregs in gliomas have been shown to express a variety of immuno-regulatory molecules, such as CD25, CTLA-4, GITR (glucocorticoid-induced TNFR family related gene), and CXCR4 at high levels." (PMID 24202450, 2013). "We investigated FOXP3 expression in normal brains and in gliomas, the most frequent of primary brain tumors." (PMID 23888189, 2012). "Phosphatidylinositol 3 kinase (PI3K) signalling, necessary to stimulate glioma invasion and migration downregulates FOXP3 expression by sequestering FOXO1 and FOXO3a factors in the cytoplasm." (PMID 23888189, 2012). "Based on these findings as well as the fact that the bone marrow represents the immediate tumor environment of glioma, bone marrow-residing Tregs expressed higher levels of Foxp3 as compared to control mice." (PMID 20339520, 2009). "The intracellular expression of Foxp3 in gated CD4+ T cells from the bone marrow of glioma-bearing mice confirmed the presence of Tregs in 20.0% ± 2.33% of the cells." (PMID 20339520, 2009). "Accumulation of Foxp3+ Tregs in syngeneic mouse gliomas has also been described and depletion of Tregs with CD25-specific immunoglobulins can induce tumor regression and improve survival in these preclinical models." (PMID 18431473, 2008). "Accumulation of Foxp3+ Tregs in human gliomas correlates with the grade of the tumor and patient survival." (PMID 18431473, 2008). "Foxp3+ Tregs accumulate within human gliomas during tumor progression and have been found to correlate with tumor grade." (PMID 18431473, 2008). "CD4+ FoxP3+ Tregs increase in developing gliomas and have an active phenotype." (PMID 40060757, 2025). "This activity of GPNMB could explain our in vivo observation, namely the reduced levels of Foxp3+ T regs and PD-1+ T cells in the glioma tissue combined with increased levels of cytotoxic cells, CD8+ cells and proliferating T cells." (PMID 38566120, 2024). "Moreover, in murine models, dysregulation of the gut microbiota downregulates the expression of Foxp3 in the brain and promotes the growth of gliomas." (PMID 39022732, 2024). "Importantly, depletion of Tregs has previously been directly linked to survival prolongation in mice with experimental gliomas, while CD4+/CD25+/FoxP3+ Treg infiltration positively correlates with clinical glioma tumour grade." (PMID 39048947, 2024). "Combined, these data indicate that neither fractionated radiation nor KCa3.1 targeting with TRAM-34 nor their combination, induced pronounced changes in the abundance of Iba1+ or CD68+ reactive microglia and CD3+, CD8+ cytotoxic or FoxP3+ regulatory T cells in the SMA-560 VM/Dk glioma model." (PMID 37996600, 2023). "Furthermore, the role of IFNAR in antitumor immune responses was highlighted through the use of glioma mouse models that showed reduced infiltration of CTLs and an increase in immunosuppressive Foxp3+ regulatory T cells in Ifnar-/- mice with induced gliomas." (PMID 37304294, 2023). "The positive correlations between both PD-1 and FOXP3 levels with tumor grade and Ki67 in gliomas appear to reinforce the finding that their expression may be correlated with a poor patient prognosis." (PMID 37621817, 2023).
glioma (continued). "In addition, dysregulation of the gut microbiota affects the balance between anti-inflammatory Tregs and pro-inflammatory Th17 cells, downregulates Foxp3 expression on tumor cells, and leads to inhibition of glioma cell growth and apoptosis." (PMID 38239850, 2023). "Microbiota manipulation could affect glioma progression and induce fluctuation of Foxp3 (a signature of Tregs) expression, indicating that the gut microbiota may influence adaptive immunity and regulate glioma progression." (PMID 36627748, 2023). "However, our experimental data proved that the GM of mice can regulate Foxp3 expression in the glioma microenvironment and affect the development of glioma." (PMID 35345443, 2022). "Therefore, further experiments are needed to explore how GM affects glioma development by regulating Foxp3 expression." (PMID 35345443, 2022). "Since FoxP3+ Tregs play a crucial role in glioma-mediated immunosuppression, we wonder whether the SOAT1 expression was associated with immunosuppression in glioma." (PMID 35646697, 2022). "Moreover, Foxp3+ Tregs in glioma can bind to CD80/CD86 on antigen-presenting cells (APCs) through CTLA-4, affecting their efficacy and thus inhibiting T lymphocyte activity." (PMID 36466873, 2022). "Overall, our results suggest that gut microbiome dysbiosis may downregulate Foxp3 expression in mouse brain to promote glioma growth." (PMID 35345443, 2022). "However, Foxp3 expression is not limited to Tregs but is also expressed in different types of tumor cells, including glioma cells." (PMID 35345443, 2022). "Therefore, we believe that GM can affect glioma growth by affecting Foxp3 expression in the glioma microenvironment." (PMID 35345443, 2022). "Immunohistochemistry (IHC) staining for Foxp3 was performed in 72 high-grade glioma specimens." (PMID 33429364, 2021). "Foxp3+ Tregs of glioma can bind to CD80 or CD86 via CTLA-4 to suppress T lymphocyte activity." (PMID 33429364, 2021). "We found a differential expression of Foxp3 in high-grade glioma tissues." (PMID 33429364, 2021). "Foxp3 expression was very different in high-grade glioma tissues." (PMID 33429364, 2021). "Moreover, intratumoral accumulation and activation of CD4+FoxP3+ Treg has been considered the principal immune escape mechanism in gliomas." (PMID 34066132, 2021). "Expressions of cyclin G2 and Foxp3 in glioma specimens was determined by immunohistochemistry." (PMID 34452627, 2021). "Additionally, we found a greater proportion of infiltrating CD4+CD25+Foxp3+ Tregs in the tumor tissue than in peripheral blood of glioma patients." (PMID 33576874, 2021). "Based on the overexpression of these factors and the existence of both MDSCs and Tregs in the glioma microenvironment, researchers hypothesize that MDSC-mediated expansion of FOXP3+ Tregs may also occur in gliomas." (PMID 30619286, 2018). "In addition, the presence of immunosuppressive infiltrates such as FoxP3+ Treg cells, M2 macrophages, and MDSC were documented in gliomas and associated with poor survival in gliomas." (PMID 27738332, 2016). "We also demonstrated using ChiP that FOXP3 is a transcriptional regulator of p21 and c-MYC supporting the idea that dysregulated expression of these factors is a major mechanism of tumorigenesis driven by the loss of FOXP3 expression in gliomas." (PMID 23888189, 2012). "FOXP3 expression was higher in low-grade gliomas than in GB." (PMID 23888189, 2012). "Foxp3 levels in these glioma cells were also significantly decreased (by 31.88%)." (PMID 22323550, 2012). "Similarly, CD4+FoxP3− T helper and CD4+FoxP3+ T regulatory cells are found clustered together in the glioma." (PMID 21060663, 2010). "The partial depletion of Foxp3+ Tregs in the murine glioma model may depend on the nature of the mAb used." (PMID 20339520, 2009).
glioma (continued). "Since FOXP3 is crucial for suppressing anti-tumor immunity, clinical validation of FOXP3 and its associated post-translational modification (PMT) proteins could provide potential therapeutic target and prognostic significance for glioma treatment." (PMID 37621817, 2023). "However, the clinical prognostic value of FoxP3+ Tregs in glioma remains controversial." (PMID 35646697, 2022). "Indeed, the nTreg population may predominate in glioma, with high FoxP3 expression also seen by another group in glioma samples and linked with higher grade and high levels of Helios transcription factor, another nTreg marker." (PMID 31973059, 2020). "FOXP3 expression in our study significantly correlated with the WHO grade and was predominantly expressed in high-grade gliomas." (PMID 37621817, 2023). "Moreover, dysregulation of the gut microbiota can affect the immune balance between anti-inflammatory Tregs and proinflammatory Th17 cells and could downregulate the expression of Foxp3 on tumor cells, leading to the growth and apoptosis inhibition of glioma cells." (PMID 36466873, 2022). "We also performed immunohistochemical staining of immune cell-specific markers including CD11b, CD14, CD56, CD11c, FOXP3, CD8 and CD4 in glioma tissues." (PMID 31377744, 2019). "Upon recurrence in primary gliomas, similar kinetic changes were found between tumor blood vessels and each TIL subset in all groups, but only CD4+ including Foxp3+ TILs, positively correlated with the density of tumor blood vessels." (PMID 29163521, 2017). "As recognised in recent years, in gliomas and other tumours CD25+ cells often represent regulatory T cells (FoxP3+), and these cells have been demonstrated to play an important role in the maintenance of peripheral tolerance." (PMID 23132370, 2013). "The average frequency of Th17 that co-expressed IFN-γ, FoxP3 and IL-4 increased from 0%, 0%, and 0% in PBS-brains to 10±4%, 22±5% and 4±3%, in glioma brains, respectively." (PMID 21060663, 2010). "Expressions of negative immune regulators like PD-1 and Foxp3 can pave way for a better understanding of the extent of immunosuppression in the glial tumor environment, which is imperative to formulate new therapeutic approaches." (PMID 37621817, 2023). "Furthermore, we randomly selected 12 glioma clinical specimens and detected some immune cell markers, including CD4, FOXP3, CD68, iNOS and CD206, to verify our bioinformatics analysis results." (PMID 37006287, 2023). "Results indicated a negative correlation between cyclin G2 and Foxp3, which uncovers a possible negative impact of cyclin G2 on tumor-infiltrating Tregs in glioma." (PMID 34452627, 2021). "Although accumulating evidence has indicated that Treg cells widely exist within glioma tissues, we did not observe any Foxp3+ Treg cells in this tumor." (PMID 34805184, 2021). "Although some studies have explored the immunosuppressive effect of Treg in glioma, the relationship between Foxp3 expression and the immune response has not yet been discussed in GBM." (PMID 33429364, 2021). "Our results indicate abundance of FoxP3+ Tregs in non-treated glioma, whereas a significant reduction in intratumoral FoxP3+ Tregs is observed with CPMV immunotherapy." (PMID 30974896, 2019). "Early work from our laboratory and independent groups identified a progressive increase in the numbers of CD25+FoxP3+ Treg with WHO grade II, III, and IV (GBM) astrocytoma, respectively, either in the peripheral circulation or within the tumor of human resected gliomas." (PMID 23720663, 2013).
glioma (continued). "Interestingly, some Th17 cells present in mouse glioma co-expressed the Th1 and Th2 lineage markers, IFN-γ and IL-4, respectively, but predominantly co-expressed the Treg lineage marker FoxP3." (PMID 21060663, 2010). "However, when the group performed univariate Cox proportional hazards analysis within glioma pathological subtypes, the percentage of cells that stained positive for FoxP3 did not seem to correlate with survival duration." (PMID 33995529, 2021). "In another cohort of 135 gliomas including 52 glioblastomas regardless of pathological type, the median survival was 43 months [(95% confidence interval [CI], 26.9—not available months) in patients whose tumours stained negatively for FoxP3." (PMID 33995529, 2021). "Moreover, in this study, we confirmed the negative correlation between cyclin G2 and Foxp3 in glioma specimens." (PMID 34452627, 2021). "However, the influences CD4+ Th2 and CD4+FOXP3+ Treg cells have within the TME have not been fully clarified in glioma." (PMID 32914058, 2018). "Therefore, the clinical outcome of patients with deeply invading cervical tumors is not influenced by the Foxp3+ cells, which is also the case in glioma and cutaneous melanoma." (PMID 26357849, 2015). "We also compared the population of Tregs in glioma bearing mice with and without CPMV immunotherapy by staining for FoxP3 expression, which is a regulatory T cells specific transcription factor." (PMID 30974896, 2019). "Subsequent observations found that thymus-derived nTreg, rather than glioma-induced iTreg, represent the predominant population of CD4+FoxP3+ T cells within brain tumors." (PMID 23720663, 2013). "In our second experiment of mice, we found that Foxp3 was highly expressed in the brain of Non-ABT mice, but not in ABT mice, indicating that the glioma growth rate of Non-ABT mice was relatively slower than that of ABT mice, which was consistent with the results of living image." (PMID 35345443, 2022). "In addition, immunofluorescence analysis showed the presence of Tregs (CD3+FOXP3+) and suppressive macrophages (GFP+CD206+) in S100a4−/− host gliomas, indicating that S100a4 is not required for lineage determination or cellular differentiation of these leukocytes." (PMID 35140215, 2022). "However, it is unclear whether CCL5 in gliomas would also trigger similar Treg inhibition toward CD8+ TILs, as we only found a negligible population (<2%) of Treg characterized as Foxp3+ CD4+ (data not shown)." (PMID 31649684, 2019).
Immunodeficiency (80 papers, 2010 to 2025). Failure of the immune system to protect the body adequately from infection, due to the absence or insufficiency of some component process or substance. "FoxP3 has been identified as a major regulator of Treg evolution and function, and mutations or inactivation of FoxP3 can cause immune disorders." (PMID 39695001, 2024). "In contrast, immunosuppressive functions of FoxP3+ CD8 T-cells are primarily detrimental since higher frequencies of these cells have been associated with immune dysfunction, viral persistence and HIV disease progression." (PMID 35967314, 2022). "Mutations of FOXP3 have been shown to cause the Scurfy phenotype of IPEX syndrome (immunodeficiency, poly-endocrinopathy, enteropathy, and X-linked) in mice and humans." (PMID 32670274, 2020). "In humans, Foxp3 mutations lead to a Treg dysfunction and an immune dysfunction, polyendocrinopathy, enteropathy, and the X-linked (IPEX) syndrome." (PMID 32322593, 2020). "Decreased FOXP3 expression causes an immune disease by subverting the suppressive function of Treg cells and converting Treg cells into effector cells." (PMID 31772947, 2019). "Five patients with known single gene mutations (three thalassaemia majors, one Fanconi anaemia and one immunodeficiency caused by variant of FOXP3-gene) showed reduced spermatogonial quantity (0.4 ± 0.5) compared to controls (P = 0.006)." (PMID 30052981, 2018). "Mutations of human FoxP3 result in dysfunction or impaired development of Tregs and lead to immunodysregulation and diverse immune disorders." (PMID 29688896, 2018). "The homologous Foxp3 mutations were proved to cause genetic disorders in humans, such as immune disorders, bowel diseases, and endocrine diseases." (PMID 29156761, 2017). "The same FOXP3 mutation was suspected in both brothers of the mother who died in early infancy with immune deficiency and hyper-IgE." (PMID 24982679, 2014). "Loss of FOXP3 function leads to Treg deficiency, resulting in lethal autoaggressive lymphoproliferation, whereas FOXP3 overexpression leads to severe immunodeficiency." (PMID 24649219, 2013). "Through the research on scurfy mice and human patients with immune disorders, multiple endocrine failure, intestinal lesions and X chromosome-associated syndrome, it has been found that transcription factor FoxP3 plays an important role in maintaining self-tolerance." (PMID 39033277, 2024). "Secondly, by activating tumor associated macrophages, myeloid-derived suppressive cells, Cd4+Foxp3+Treg cells or Th17 cells, inflammation could impair the immune response within tumors, promoting immune deficiency and cancer progression." (PMID 37063910, 2023). "Disturbances in the proper functioning of the Foxp3 protein in the human body (usually caused by mutations within the coding sequences) dysregulate the immune homeostasis and leads to the development of diseases called immunodeficiencies." (PMID 35207219, 2022). "Fourteen studies hypothesized that induction of FOXP3, causing an increase in Treg, is the mechanism through which Aza/Dac can be used as a potential treatment for the different immune disorders." (PMID 33407530, 2021). "For example, the immunodeficiency IPEX is caused by mutations in the gene FOXP3." (PMID 25904912, 2015). "The functional significance of FoxP3 for Treg activity is further supported by such findings as the following: loss of FoxP3 function caused autoaggressive lymphocyte proliferation, whereas excessive FoxP3 expression resulted in severe immunodeficiency." (PMID 23983771, 2013). "This raises questions with regards to previous associations of FOXP3 promoter demethylation with immune disease states which were based on unfractioned blood analyses, which may need to be revisited by measuring IPDR demethylation in sorted specific T cell subsets." (PMID 26500760, 2015). "In these mice, depletion of Foxp3-expressing cells can be induced by treatment with diphtheria toxin (DT) to study various immune disorders." (PMID 38773985, 2024).